HTT (huntingtin)
Diseases named in the same sentence as HTT in open-access papers (continued):
Sharing a sentence is not in itself a finding about the gene and the disease.
Huntington disease (continued). "In Huntington’s disease (HD), a dominantly inherited neurodegenerative disorder, both cognitive impairments and abnormal tau expression have been reported to occur, along with the accumulation of the mutant huntingtin protein." (PMID 40047995, 2025). "Polyglutamine (polyQ) tract expansion (≥ 36 amino acids) within the N‐terminal region of the Huntingtin protein (Httex1) causes Huntington's disease (HD), for which the underlying causes are not well‐understood." (PMID 40289673, 2025). "Similarly, in cellular and mouse models of Huntington’s disease, it was observed that the huntingtin/HAP1/dynactin complex was altered." (PMID 41254423, 2025). "Huntington’s Disease (HD) is a genetic disorder characterized by movement and cognitive impairments, including chorea and coordination loss, stemming from mutations in the HTT gene encoding huntingtin." (PMID 40291849, 2025). "Huntington’s disease (HD) is caused by the expansion of CAG trinucleotide repeats in the HTT gene, which encodes huntingtin protein, resulting in the production of mutant huntingtin (mHTT)." (PMID 41516242, 2025). "Huntington’s disease is a neurodegenerative disorder, characterized by abnormal long CAG repeat expansions in the Huntingtin gene, that causes the expansion of a polyglutamine (polyQ) stretch in the huntingtin protein (HTT)." (PMID 40007760, 2025). "These strategies could enhance the clearance of toxic protein aggregates like amyloid-beta in Alzheimer’s disease or mutant huntingtin in Huntington’s disease, thus reducing neurodegeneration." (PMID 41190025, 2025). "Huntington’s disease: Huntington’s disease (HD), a fatal neurodegenerative disorder, arises from pathological expansions of a polyglutamine (polyQ) tract in exon 1 of the huntingtin protein (HTT)." (PMID 40727669, 2025). "Moreover, Kv3.4 expression is reduced in Huntington’s disease, which similar to SBMA is caused by exonic CAG expansions in the gene coding for huntingtin." (PMID 40653481, 2025). "Huntington's disease (HD) is a fatal neurodegenerative disorder caused by a CAG repeat expansion in the Huntingtin (HTT) gene, with no disease-modifying therapies currently available." (PMID 41030958, 2025). "Our fibromyalgia variant is located in exon 58 of the large HTT gene (which spans 67 exons and 180 kb) and does not lie in this repeat region, but is part of the Huntington’s disease-associated “A1” haplotype found in Europeans53." (PMID 41001472, 2025). "Huntington’s disease (HD) is an autosomal dominant neurodegenerative disorder caused by a single mutation—specifically, an abnormal expansion of cytosine-adenine-guanine (CAG) repeats within the huntingtin (HTT) gene." (PMID 40869897, 2025). "In our previous work, we demonstrated that the HTT gene can influence cognitive function, personality traits, and the risk of progression to AD in patients without a family history of Huntington’s disease and with a normal number of CAG repeats." (PMID 40844528, 2025). "Huntington’s disease is an autosomal dominant disorder characterized by cognitive, behavioural and motor disturbances caused by an expansion of the CAG triplet (>35 repeats) in exon 1 of the HTT gene, leading to an abnormal polyglutamine tract." (PMID 40385290, 2025). "There are no disease-modifying treatments available for Huntington’s disease (HD), a neurodegenerative disease caused by a genetic mutation in the Huntingtin gene." (PMID 41226707, 2025). "Similarly, mutant huntingtin protein drives Huntington’s disease (HD), and TAR DNA-binding protein (TDP)-43 aggregates are implicated in Amyotrophic Lateral Sclerosis (ALS)." (PMID 40430519, 2025). "Huntington’s disease (HD) is a progressive neurodegenerative disorder caused by an expanded CAG trinucleotide repeat in the HTT gene on chromosome 4, leading to the production of mutant huntingtin protein (mHtt)." (PMID 41239019, 2025).
Huntington disease (continued). "In Huntington’s disease (HD), the CAG nucleotide expansion in HTT gene causes a poly-Q expansion in HTT protein which decreases its interaction with HIP14 and HIP14L, consequently, their enzymatic activity is lowered, presumably resulting in the mislocalization of multiple synaptic proteins." (PMID 41474785, 2025). "Moreover, a similar correlation was observed in cells overexpressing the polyglutamine form of Huntingtin (HTT Q74 exon 1), an essential protein involved in Huntington’s disease, and in cells treated with Aβ oligomers." (PMID 40537797, 2025). "Moreover, in Huntington’s disease (HD), a mouse model expressing mutant huntingtin protein shows increased LD accumulation in primary striatal neurons and glia, associated with defects in the autophagic pathway." (PMID 41404624, 2025). "The eventual modification of the HTT protein is hypothesized to reduce the toxicity of mutant HTT involved in Huntington Disease (HD)." (PMID 41066632, 2025). "Advanced neurodegenerative disease is characterized by insoluble protein aggregates, including intraneuronal neurofibrillary tangles (NFTs) in Alzheimer’s disease, Lewy bodies containing α-synuclein in Parkinson’s disease, and huntingtin inclusions in Huntington’s disease." (PMID 41438474, 2025). "Similarly, in Huntington’s disease, although the mutant huntingtin protein (HTT) is typically overexpressed, studies using induced pluripotent stem cells (iPSCs) have shown that elevated levels of UBR5 can promote the degradation of the mutant HTT protein." (PMID 39857943, 2025). "In Huntington’s disease patients, the huntingtin gene Htt contains a prolonged CAG repeat." (PMID 40589526, 2025). "Our study elucidates the molecular mechanism responsible for BACHD-SD mice ameliorated phenotype and underscores a critical need to identify enzymes responsible for regulating HTT phosphorylation to exploit their potential as therapeutic Huntington’s disease targets." (PMID 39779371, 2025). "Huntington disease (HD) is a hereditary neurodegenerative disease characterized by a triad of motor, psychiatric and cognitive signs caused by an unstable Cytosine-Adenine-Guanine (CAG) repeat expansion mutation in the huntingtin (HTT) gene." (PMID 41094130, 2025). "Huntington’s disease (HD) is an autosomal dominant neurodegenerative disorder caused by an expanded and unstable cytosine–adenine–guanine (CAG) trinucleotide repeat in the huntingtin (HTT) gene." (PMID 41462929, 2025). "Huntington's Disease (HD) is a neurodegenerative disorder characterised by an expanded CAG repeat mutation in the HTT gene, causing an extended polyglutamine tract in the huntingtin (htt) protein." (PMID 40542543, 2025). "The role of copper in Huntington’s disease (HD) goes beyond directly binding to mutant huntingtin (mHTT) and promoting its aggregation; it also involves exacerbating the pathological process through the regulation of immune responses and oxidative stress mechanisms." (PMID 40510202, 2025). "Moreover, the transfer of mutant huntingtin protein into grafted neurons within the Huntington’s disease (HD) mouse model underscores the relevance of this system for investigating mechanisms of pathological protein propagation." (PMID 40001985, 2025). "Huntington’s disease (HD), a genetic neurodegenerative condition characterized by progressive choreiform movements and cognitive and behavioral symptoms, is caused by the presence of > 35 CAG trinucleotide repeats within the first exon of the huntingtin gene." (PMID 41340001, 2025). "Huntington’s disease (HD) is caused by mutations in the huntingtin (HTT) gene, which results in an expanded CAG trinucleotide repeat encoding a polyglutamine (polyQ) tract within the HTT protein." (PMID 40659647, 2025).
Huntington disease (continued). "Huntington’s disease (HD) is a neurological conditioncausedby an excessive expansion of CAG repeats in the Huntingtin (HTT) gene.Although experiments have shown an altered epigenetic landscape andchromatin architecture upon HD development, the structural consequenceson the HTT gene remain elusive." (PMID 40287840, 2025). "In Huntington’s disease (HD, OMIM #143100), modifications in DNA methylation have been linked with the expression of mutant huntingtin (HTT), and DNA methylation may also be in part responsible for the tissue-specific HTT transcription." (PMID 40508170, 2025). "Huntington’s disease (HD) arises from expanded CAG repeats in exon 1 of the Huntingtin (HTT) gene." (PMID 38786052, 2024). "Historically, the aggregated proteins were assigned to defined clinical conditions: Aβ and Tau to AD, α-synuclein to the synucleinopathies Parkinson’s disease (PD), dementia with Lewy bodies (DLB) and multiple system atrophy (MSA) and Huntingtin to Huntington’s disease (HD)." (PMID 39625512, 2024). "Additionally, the use of ASO in a mouse model of Huntington’s disease significantly reduced the mutant HTT (mHTT) protein, resulting in improved neurological function." (PMID 38920997, 2024). "In addition, beneficial effect of BECN1 overexpression was unveiled in murine huntingtin (HTT) model of Huntington’s disease (HD)." (PMID 38722788, 2024). "Finally, in Huntington’s disease, the administration of Tominersen (developed by ROCHE) has been inconclusive due to the allelic heterogeneity presented in the HTT gene mutation." (PMID 39684197, 2024). "We are also interested in the effect of Sparcl1 fusion on known aggregation-prone proteins in the field of neurodegenerative diseases, such as amyloid β in Alzheimer’s disease, α-synuclein in Parkinson’s disease, huntingtin protein in Huntington’s disease, and SOD1 in amyotrophic lateral sclerosis." (PMID 38474544, 2024). "Huntington’s disease (HD) is a genetic neurological disorder caused by an expansion mutation of the trinucleotide (CAG) repeat in exon 1 of the HTT (IT15) gene, encoding a 350-kDa protein termed Huntingtin (HTT)." (PMID 39578834, 2024). "Currently, there are no therapies available for Huntington’s disease, and the process by which Huntingtin protein aggregates and causes the disease is not fully understood." (PMID 39146256, 2024). "Together, these indicate that the branching function of Arp2/3 is essential for CME, and that the altered function of Arp2/3 by HTT Q138 aggregates may be one of several possible mechanisms by which CME is inhibited in Huntington’s disease." (PMID 39382268, 2024). "In Huntington’s disease, another neurodegenerative disease affecting the basal ganglia, recent work suggests that the polyglutamine expansion of huntingtin, definitive of the condition, promotes ribosome stalling rescued through depletion of the huntingtin protein." (PMID 38397070, 2024). "Huntington’s disease (HD) is an incurable human genetic disease with dominant inheritance and is caused when the CAG codon expands beyond the threshold of 36 in the IT15 gene, which is also known as the HTT gene and codes for the protein hungtingtin." (PMID 38190040, 2024). "This strategy has been extensively investigated in Huntington’s disease to improve the non-allele-specific huntingtin (HTT)-lowering gapmer ASO tominersen, of which a phase III trial was stopped due to worsening clinical outcomes." (PMID 38993932, 2024). "Post-mortem brain tissue from Huntington’s disease (HD) patients and striatal cells from mice with mutant huntingtin knock-in exhibit a pathological-dependent reduction in mitochondrial numbers, and both mitochondrial respiration and ATP production are markedly impaired." (PMID 39795902, 2024).
Huntington disease (continued). "The behavioral and molecular characterization was performed for Huntington's disease mouse models expressing a fragment of the human HTT gene, with mutation of ~100 CAG repeats, in the nontranslated version (HD/100CAG) and the translated version (HD/100Q)." (PMID 39604147, 2024). "Artificial ZFPs designed to bind long CAG repeats and fused with the KRAB domain were successfully used to repress the mutant huntingtin (htt) gene in STHdh cells, a mesothelial cell line from a heterozygous patient with Huntington’s disease (HD), and in the brain of R6/2 HD-model mice." (PMID 38791270, 2024). "Huntington’s disease (HD) is a genetic neurodegenerative disorder caused by an expansion of a CAG triplet repeat stretch within the first exon of the huntingtin gene, which results in a mutant form of the huntingtin protein." (PMID 38841098, 2024). "Both human iPSCs and brain telencephalic organoids have been developed to evaluate the neuronal defects associated with Huntington’s disease (HD), a neurodegenerative autosomal dominant disease with a late onset caused by a CAG expansion in the huntingtin (HTT) gene." (PMID 38256087, 2024). "Huntington’s disease (HD) is a fatal autosomal dominant neurodegenerative disorder characterized by an expanded trinucleotide CAG (cytosine-adenine-guanine) repeat in exon 1 of the HTT (huntingtin) or IT15 gene (located at 4p.16.3)." (PMID 38978875, 2024). "Huntington's disease (HD) is a rare autosomal dominant disorder caused by a mutation in the HTT gene on chromosome 4, which leads to an overproduction of the mutant huntingtin (m-Htt) protein that aggregates in brain regions, causing neuronal dysfunction and degeneration." (PMID 39433509, 2024). "Huntington’s disease (HD) is an autosomal dominant neurodegenerative condition caused by a CAG expansion repeat in exon 1 of the huntingtin gene, leading to an accumulation of mutant huntingtin protein (mhtt)." (PMID 39361164, 2024). "HAP1 known as a protein identified could be interacted with protein huntingtin in Huntington’s disease (HD), and is mainly located in the hippocampus and caudate nucleus." (PMID 37609072, 2023). "Huntingtin-lowering strategies are central to therapeutic approaches for Huntington’s disease." (PMID 38116140, 2023). "Administration of AAV5-miHTT suppressed mutant HTT mRNA, resulting in almost complete prevention of mutant HTT aggregate formation and suppression of DARPP-32-associated neuronal dysfunction in a rat model for Huntington’s disease." (PMID 36992407, 2023). "In addition, CMA is also reported to degrade TDP-43 and huntingtin (Htt), which are linked to amyotrophic lateral sclerosis (ALS) and Huntington’s disease (HD), respectively." (PMID 37762105, 2023). "Huntington’s disease arises from a toxic gain of function in the huntingtin (HTT) gene." (PMID 37684045, 2023). "In vivo, specifically targetting mutant HTT in the CNS led to an amelioration of a number of molecular and neurological phenotypes in HD mouse models and became a valid therapeutic strategy for Huntington’s disease." (PMID 37138658, 2023). "Huntington’s disease is a neurodegenerative disorder characterised by progressive motor and cognitive deficits caused by an expansion of CAG (glutamine-encoding) repeats within the exon 1 of the HTT gene." (PMID 37680383, 2023). "The use of CRISPR interference (CRISPRi) to repress the expression of mutant with relative preservation of wild-type huntingtin may represent a potential therapeutic strategy to delay disease progression in a mouse model of Huntington’s disease." (PMID 37117485, 2023). "Huntington’s disease (HD) is an autosomal-dominant inherited, neurodegenerative disorder caused by a cytosine–adenine–guanine (CAG) polyglutamine repeat expansion in the first exon of the HTT gene encoding the huntingtin protein." (PMID 37047023, 2023).
Huntington disease (continued). "Research into Huntington’s disease (HD), a neurodegenerative disorder caused by a trinucleotide repeat expansion in the gene (HTT) encoding the huntingtin protein, found that mutant huntingtin interacts directly with HAT proteins, resulting in altered histone acetylation." (PMID 36590248, 2023). "Huntington’s disease (HD) is a devastating monogenic neurodegenerative disease characterized by early, selective pathology in the basal ganglia despite the ubiquitous expression of mutant huntingtin." (PMID 37814059, 2023). "Huntington’s disease is an autosomal dominant progressive neurodegenerative disorder characterized by > 35 CAG trinucleotide repeats in the gene that codes for the Huntingtin protein, which is essential for neuron function and is most concentrated in the brain." (PMID 37424016, 2023). "In this case, increased solubility of pathogenic proteins may lead to a more deleterious effect, as shown by some studies of huntingtin in Huntington’s disease." (PMID 38201212, 2023). "Dysfunction in the GS could potentially contribute to the accumulation of mutant huntingtin protein and exacerbate neuronal damage in Huntington’s disease." (PMID 38139290, 2023). "Furthermore, intracellular aggregation of tau in AD, α-synuclein in PD, and huntingtin in Huntington's disease (HD) also impairs proteasomal activity to enhance neuropathies." (PMID 36910151, 2023). "Huntington’s disease (HD), a neurodegenerative disease with an autosomal dominant pattern of inheritance, results from an expansion of CAG repeats in the IT15 gene encoding the Huntingtin (HTT) protein required for axonal transport." (PMID 36671323, 2023). "In Huntington’s disease (HD), alterations in oxidative phosphorylation occur due to increased aggregation of the mHTT protein, also known as the Huntingtin gene (HTT), whose main function is the regulation of the passage from DNA to mRNA for the formation of proteins." (PMID 37760929, 2023). "Huntington’s disease (HD) is a heritable, fully penetrant, autosomal neurodegenerative disease caused by a CAG trinucleotide expansion within the first exon of the Huntingtin (HTT) gene, leading to an expanded polyglutamine (polyQ) stretch at the N-terminal portion of the encoded HTT protein." (PMID 37727506, 2023). "Huntington’s Disease (HD) is an autosomal dominant chronic neurodegenerative disease, caused by the expansion of a CAG (cytosine, adenine, and guanine) repeat in the huntingtin gene that promotes huntingtin’s aggregation, leading to deposition of cytoplasmic and intranuclear inclusion bodies." (PMID 36768141, 2023). "Huntington’s disease (HD) is a fatal autosomal dominant neurodegenerative disease arising from the expansion of a glutamine-coding CAG tract near the 5′ end of huntingtin (HTT)." (PMID 37684045, 2023). "Huntington’s disease (HD) is an autosomal dominant, fully penetrant neurodegenerative disorder caused by an inherited CAG (polyglutamine) repeat expansion in the huntingtin (HTT) gene on chromosome 4p16.3 resulting in the production of a mutant huntingtin (mHTT) protein." (PMID 36830075, 2023). "Huntington’s disease (HD) is a rare, dominantly-inherited, neurodegenerative disorder and is caused by an abnormal amplification of CAG repeats (encoding for glutamine) in the huntingtin (HTT) gene." (PMID 37013480, 2023). "Huntington’s disease (HD) is an autosomal dominant neurodegenerative disorder that is defined by a pathological CAG expansion exceeding 35 repeats in Exon1 of the huntingtin (HTT) gene." (PMID 36651994, 2023). "Huntington’s disease (HD) [OMIM:143100] is a progressive and fatal neurodegenerative disease caused by a CAG repeat expansion in exon 1 of the Huntingtin gene (HTT), which results in an expanded polyglutamine stretch in the Huntingtin protein (HTT)." (PMID 36670467, 2023).